ING3 (inhibitor of growth family member 3)
Description:
Component of the NuA4 histone acetyltransferase (HAT) complex which is involved in transcriptional activation of select genes principally by acetylation of nucleosomal histones H4 and H2A. This modification may both alter nucleosome - DNA interactions and promote interaction of the modified histones with other proteins which positively regulate transcription. This complex may be required for the activation of transcriptional programs associated with oncogene and proto-oncogene mediated growth induction, tumor suppressor mediated growth arrest and replicative senescence, apoptosis, and DNA repair. NuA4 may also play a direct role in DNA repair when directly recruited to sites of DNA damage. Component of a SWR1-like complex that specifically mediates the removal of histone H2A.Z/H2AZ1 from the nucleosome.
Synonyms: p47ING3; FLJ20089; Eaf4; MEAF4
Tractability: PROTAC: UniProt records ubiquitination sites on it; ubiquitination databases record sites on it; its protein half-life has been measured.
Gene: Protein-coding gene on chromosome 7 (120,950,763 to 120,977,216, forward strand). Ensembl gene ENSG00000071243.
Subcellular location: Nucleus
Subcellular location (Human Protein Atlas): Nucleoplasm
Pathways (Reactome):
Chromatin organization: HATs acetylate histones
Gene Ontology:
Molecular function: histone H2A acetyltransferase activity; histone H3K4me3 reader activity; histone H4 acetyltransferase activity; histone H4K12 acetyltransferase activity; histone H4K16 acetyltransferase activity; histone H4K5 acetyltransferase activity; histone H4K8 acetyltransferase activity
Biological process: positive regulation of double-strand break repair via homologous recombination; regulation of cell cycle; positive regulation of DNA-templated transcription; positive regulation of transcription by RNA polymerase II; regulation of apoptotic process; regulation of double-strand break repair; chromatin remodeling
Cellular component: NuA4 histone acetyltransferase complex; nucleoplasm; nucleosome; piccolo histone acetyltransferase complex; Swr1 complex; nucleus
Genetic constraint (gnomAD): Loss-of-function variants: 5 observed, 37.97 expected, observed/expected ratio (o/e) 0.13, 90% interval 0.068 to 0.28. The upper end of that interval is the gene's LOEUF score, 0.28, which puts it in group 1 of 6, group 1 being the genes least tolerant of losing a copy. Missense variants: 222 observed, 334.11 expected, observed/expected ratio (o/e) 0.66, 90% interval 0.6 to 0.74. Synonymous variants: 121 observed, 128.3 expected, observed/expected ratio (o/e) 0.94, 90% interval 0.81 to 1.1.
Homologues: Orthologues: chimpanzee ING3 (100% identical), macaque ING3 (99% identical), dog ING3 (99% identical), rabbit ING3 (99% identical), guinea pig ING3 (98% identical), pig ING3 (98% identical), rat Ing3 (97% identical), mouse Ing3 (96% identical), tropical clawed frog ing3 (83% identical), zebrafish ing3 (83% identical), Drosophila melanogaster Ing3 (48% identical). Paralogues in human: ING5 (23% identical), ING2 (22% identical), ING4 (22% identical), ING1 (22% identical).
Diseases named in the same sentence as ING3 in open-access papers:
ING3 is named in the same sentence as 30 diseases in open-access papers, as found by Europe PMC text mining. Sharing a sentence is not in itself a finding about the gene and the disease. The quoted sentences say what the papers report.
prostate carcinoma (12 papers, 2016 to 2025). A carcinoma that arises from epithelial cells of the prostate gland. "ING3 is a stoichiometric member of the TIP60 lysine acetyltransferase complex implicated in prostate cancer development." (PMID 28511652, 2017). "Interestingly, increased copy number of ING3 along with overexpression and deregulation of ING3 have recently been linked to poor outcomes in prostate cancer patients and castrate-resistant prostate cancer cell lines (34, –, 36)." (PMID 27281824, 2016). "Additionally, ING3 is linked with poor disease prognosis in specific prostate cancer subgroups." (PMID 38813086, 2024). "Although ING3 was assigned tumour suppressor candidate status in some types of cancers, including prostate cancer, some studies suggest it acts to promote growth." (PMID 40149370, 2025). "In contrast to its putative tumour suppressor status, recent studies assign ING3 an oncogenic role in prostate cancer, based on a higher survival rate of human prostate cancer patients with lower ING3 levels." (PMID 40149370, 2025). "Previous studies have shown that ING3 promotes prostate cancer growth by activating the androgen receptor, and PHF20 promotes glioblastoma cell malignancies through a WISP1/BGN‐Dependent pathway." (PMID 39538416, 2024). "Overall, ING1 and 2 are identified as AR-corepressors inhibiting androgen signaling, while ING3 is known to act as AR-coactivator playing role in prostate cancer pathogenesis." (PMID 36056353, 2022). "Using a high-throughput tissue microarray approach consisting of benign prostate hyperplasia and prostate cancer samples, we have validated that ING3 protein levels are elevated in prostate cancer, corresponding to cBioPortal genomic data." (PMID 33925563, 2021). "On the other hand, ING3 levels positively correlate with poor survival prognosis of prostate cancer (PCa) patients." (PMID 34439818, 2021). "Consistent with an oncogenic role, gene-silencing experiments revealed that ING3 is required for the proliferation of breast, ovarian, and prostate cancer cells." (PMID 29381681, 2018). "We observed elevated levels of ING3 in prostate cancer samples, which correlated with poorer patient survival." (PMID 29381681, 2018). "In contrast to the majority of previous reports suggesting tumor suppressive functions in other cancers, our observations identify a clear oncogenic role for ING3, which acts as a co-activator of AR in prostate cancer." (PMID 28511652, 2017). "This study has also validated ING3 as a novel prognostic biomarker that can dramatically improve prediction of overall survival in prostate cancer, particularly in cases with low levels of AR." (PMID 28511652, 2017). "Cell viability and migration assays were performed in prostate cancer cell lines using scrambled siRNA or siRNA targeting ING3." (PMID 28511652, 2017). "Including ING3 levels with currently used indicators such as the Gleason score provides more accurate prognosis in primary prostate cancer." (PMID 28511652, 2017). "In this study we show that ING3 regulates the AR pathway in prostate cancer by virtue of acting as a scaffolding component of the TIP60 complex, promoting AR acetylation, its nuclear translocation, and the activation of androgen-responsive genes." (PMID 28511652, 2017). "(A) Lysates from three AR-positive prostate cancer cell lines were subject to western blotting with antibodies against ING3, GAPDH, and actin." (PMID 28511652, 2017). "Together, these data identify ING3 as a proto-oncogene in PC by regulating the AR pathway through acetylation, and identify it as a novel prognostic biomarker for primary prostate cancer." (PMID 28511652, 2017). "Our results showed the epigenetic regulation of ING3 via H3K27me3 in prostate cancer suggesting putative tumor suppressor gene silencing by histone methylation in prostate cancer." (PMID 28403887, 2017). "Binding of ING3 with histone mark H3K4me3 prevents EMT in prostate cancer cells." (PMID 38813086, 2024).
prostate carcinoma (continued). "In agreement with yeast models, we found that ING3 is required for proliferation of breast, ovarian, and prostate cancer cells, suggesting that it may function as an oncoprotein instead of a tumour suppressor." (PMID 33925563, 2021). "Furthermore, downregulation of ING3 in prostate cancer cell lines resulted in reduced growth along with upregulation in a cohort of prostate cancer tissues suggesting an oncogenic role in progression of prostate cancer metastases." (PMID 31905726, 2019). "The expression of ING3 was assessed by IHC on a human prostate cancer tissue microarray (TMA)." (PMID 29381681, 2018). "Conversely, ING3 knockdown inhibits prostate cancer cell growth and invasion." (PMID 28511652, 2017). "In agreement with in vitro observations, analysis of The Cancer Genome Atlas (TCGA) data (n = 498) and a prostate cancer tissue microarray (n = 256) show that ING3 levels are higher in aggressive prostate cancers, with high levels of ING3 predicting shorter patient survival in a low AR subgroup." (PMID 28511652, 2017). "However, ING3 knockdown also reduced the growth and migration of AR-negative prostate cancer cells, DU145 and PC3, indicating its role in AR-independent pathways." (PMID 28511652, 2017). "Moreover, knockdown of ING3 inhibits PC cell growth, indicating that ING3 plays an oncogenic role in prostate cancer." (PMID 28511652, 2017). "(B) mRNA levels of ING3 were normalized to actin in three prostate cancer cell lines." (PMID 28511652, 2017). "Biopsies of 265 patients with prostate cancer were stained for ING3, pan-cytokeratin, and DNA." (PMID 28511652, 2017). "We find that ING3 levels and AR activity positively correlate in prostate cancer." (PMID 28511652, 2017). "Indeed, increased ING3 levels in prostate cancer patient samples correlate with poor survival." (PMID 33925563, 2021). "Thus, it is suggested that ING3 acts as an oncogene in prostate cancer (PCa)." (PMID 34439818, 2021). "The inhibitor of growth family member 3 (ING3) is an epigenetic regulator, whose role in prostate cancer is unknown." (PMID 40149370, 2025). "By physically interacting with both the AR and the TIP60 complex in the cytoplasm, ING3 directs HAT activity to the immediate vicinity of the AR, enhancing AR activation and nuclear translocation, resulting in the development and progression of prostate cancer." (PMID 40149370, 2025).
breast carcinoma (9 papers, 2016 to 2025). "High nuclear ING3 levels are linked with improved prognosis, suggesting its potential as a prognostic indicator in breast cancer management." (PMID 38813086, 2024). "In human MCF7 mammary carcinoma cells, loss of H3K4me3 binding through PHD-mutated ING3 leads to decreased apoptosis upon DNA damage, supporting wild-type ING3 tumour-suppressive function." (PMID 40149370, 2025). "This function of ING3 is notable in breast cancer, where nuclear ING3 expression is considerably reduced compared to normal tissues." (PMID 38813086, 2024). "ING3’s diminished nuclear expression in breast cancer correlates with aggressive disease via p21 signaling, while ING4’s involvement in multiple regulatory pathways, including the NF-κB/miR-155 axis, mitigates tumor progression." (PMID 38813086, 2024). "ING3 level is markedly decreased in breast cancer where its expression is closely correlated with cancer prognosis." (PMID 35845928, 2022). "While, in breast cancer tissues, ING3 was principally located in the cytoplasm, and was rarely expressed both in the cytoplasm and nucleus." (PMID 33469513, 2020). "The nuclear ING3 was negatively related with histological grade, which suggests that the decreased expression of ING3 in the nucleus was involved in the differentiation and played a continued role in the advancement and development of breast cancer." (PMID 33469513, 2020). "In this study, we investigated the expression of ING3 and determined its prognostic value in breast cancer." (PMID 33469513, 2020). "To investigate the expression of ING3 in breast cancer, we performed the immunohistochemistry staining on TMA slides." (PMID 33469513, 2020). "Multivariate Cox regression analysis of prognostic variables including classical prognostic factors and nuclear ING3 for 5-year OS in 211 cases of breast cancer patients." (PMID 33469513, 2020). "Multivariate Cox regression analysis of prognostic variables including classical prognostic factors and nuclear ING3 for 5-year DFS in 211 cases of breast cancer patients." (PMID 33469513, 2020). "The immunohistochemistry was performed to evaluate the expression of ING3 in tissue microarrays (TMA) including breast cancer tissues (n=211) and normal breast tissues (n=50)." (PMID 33469513, 2020). "Meanwhile, we also observed that, ING3 was mainly expressed in the cytoplasm in breast cancer tissues, and the expression of ING3 in the nucleus was significantly decreased." (PMID 33469513, 2020). "The χ2 test showed that the expression of nuclear ING3 in breast cancer tissues was significantly lower than that in normal breast tissues (P<0.001)." (PMID 33469513, 2020). "This study implemented a comprehensive analysis of the expression of ING3 in breast tissue for the first time, which provided a new idea and direction for better comprehensive understanding of breast cancer." (PMID 33469513, 2020). "In our study, we found that there was a correlation between the downregulation of ING3 in nucleus and clinicopathologic characters in breast cancer." (PMID 33469513, 2020). "Compared with normal breast tissues, the expression of ING3 in nucleus was remarkably reduced in breast cancer tissues." (PMID 33469513, 2020). "On the other hand, the nuclear ING3 was also negatively correlated with lymph node metastasis, which suggested that nuclear ING3 was related to the migration and metastasis of breast cancer." (PMID 33469513, 2020). "The ration of the nuclear ING3 high expression was 46.4% (98/211) in breast cancer tissues, was 10% in normal breast tissues." (PMID 33469513, 2020). "Our study comprehensively described the expression of ING3 in breast cancer for the first time and proved that it was an independent prognostic predictor of breast cancer, as well as a new idea for study of breast cancer." (PMID 33469513, 2020).
breast carcinoma (continued). "The silencing of ING3 in breast cancer, ovarian cancer, and PC cell line models led to inhibition of proliferation characterised by a G1/S arrest accompanied by an induction of apoptosis." (PMID 29381681, 2018). "Analysis of various cancer databases showed a significant increase in the copy number of ING3 in breast cancer, melanoma cancer, ovarian cancer, and PC patients." (PMID 29381681, 2018). "While, the members of the ING family are highly homologous, whether the expression of ING3 relates to the prognosis of breast cancer is still elusive." (PMID 33469513, 2020). "Importantly, multivariate Cox regression analysis suggested that the reduced expression of ING3 in nucleus was an independent prognostic factor in breast cancer." (PMID 33469513, 2020). "The nuclear ING3 expression and clinicopathological parameters in breast cancer." (PMID 33469513, 2020). "In breast cancer tissues, ING3 protein was principally detected in the cytoplasm." (PMID 33469513, 2020). "Similarly, our survival analysis also showed that in luminal-type breast cancer and lymph node metastasis group, the lower nuclear ING3 expression, the poorer 5-DFS and 5-OS." (PMID 33469513, 2020). "One possible explanation for this discrepancy was that the nuclear to cytoplasm translocation of ING3 may be a partial reason for significantly reduce of nuclear ING3 in breast cancer tissues." (PMID 33469513, 2020). "To investigate whether the decreased nuclear ING3 staining serve as a prognostic biomarker in breast cancer, we followed all of the 211 patients and used the Kaplan-Meier method and log-rank test to analyze the follow-up data." (PMID 33469513, 2020). "In breast cancer tissues, the expression of nuclear ING3 in pathological grade III group (13/52) was lower than that in pathological grade I–II group (85/159) (χ2 = 12.759, P<0.001), which suggested that the nuclear ING3 expression was negatively correlated with the histological grade (P<0.001)." (PMID 33469513, 2020). "Next, we explored whether the expression of nuclear ING3 affects the prognosis of different molecular subtypes of breast cancer." (PMID 33469513, 2020). "In addition, the nuclear ING3 was positively correlated with ER and PR status, which were closely related to endocrine therapy of breast cancer." (PMID 33469513, 2020). "Collectively, these results indicated that the high expression of nuclear ING3 might be a good prognostic biomarker of breast cancer." (PMID 33469513, 2020). "Moreover, the independent prognostic biomarker of nuclear ING3 in breast cancer patients was revealed based on the multivariate Cox regression analysis." (PMID 33469513, 2020). "Therefore, the mechanism of the decreased expression of nuclear ING3 in breast cancer needs to be further studied." (PMID 33469513, 2020). "Precisely, our data demonstrate that (i) ING3 levels are elevated in PC patients and correlate with poor outcome; (ii) ING3 is required for the proliferation of breast cancer, ovarian cancer, and PC cell lines; and (iii) ING3 expression is sufficient to elicit anchorage-independent growth." (PMID 29381681, 2018). "The requirement of ING3 for the proliferation of breast cancer, ovarian cancer, and PC cells and its elevated levels in prostate tumours, which also correlate with poor survival, define ING3 as a novel marker of poor prognosis and a potential therapeutic target." (PMID 29381681, 2018). "In addition, we also found that nuclear ING3 could predict the prognosis of breast cancer patients in lymph node metastasis (LN+) group (P=0.043 and P=0.019), but not in lymph node negative (LN-) group (P=0.221 and P=0.499)." (PMID 33469513, 2020). "In conclusion, our study showed that the expression of nuclear ING3 was significantly decreased in breast cancer, which was closely related to the clinicopathological parameters and might be used as an independent prognostic factor to evaluate the 5-DFS breast cancer patients." (PMID 33469513, 2020).
breast carcinoma (continued). "However, few studies on ING3 in breast cancer have been reported." (PMID 33469513, 2020). "As the homologous of ING4, ING3 might also be related to endocrine therapy of breast cancer." (PMID 33469513, 2020). "Then, we used the same method to study the correlation between the nuclear ING3 expression and the status of ER, PR, and HER2 in breast cancer tissues." (PMID 33469513, 2020). "Meanwhile, the rate of high expression nuclear ING3 in breast cancer with luminal-type was higher than that with HER2-enriched and TNBC, which suggested that nuclear ING3 might play a role in distinguishing different subtypes of breast cancer." (PMID 33469513, 2020). "Although the nuclear ING3 expression was significantly reduced in breast cancer tissues compared with normal breast tissues, it is not clear how the nuclear ING3 is reduced." (PMID 33469513, 2020). "Moreover, Kaplan-Meier curves demonstrated that the reduced expression of ING3 in nucleus was correlated with a poorer 5-DFS and 5-OS of breast cancer patients." (PMID 33469513, 2020). "Furthermore, the correlation between the nuclear ING3 expression and clinicopathologic variables, the patient of 5-year disease-free survival (5-DFS) and 5-year overall survival (5-OS) were analyzed in breast cancer." (PMID 33469513, 2020). "Although there is no related report of ING3 in breast cancer at this stage, ING4 and ING5, as members of the ING family, participate in the occurrence of breast cancer." (PMID 33469513, 2020).